EGFR (epidermal growth factor receptor)
Diseases named in the same sentence as EGFR in open-access papers (continued):
Sharing a sentence is not in itself a finding about the gene and the disease.
tumor (continued). "Some of these proteins were tumor suppressors, including Rb, FOXO3, and p27, and many proteins were kinases and involved in the regulation of cell proliferation, differentiation, and apoptosis, such as c-KIT, AKT, EGFR, MAPK1/3, PRKCA, SRC, ACVRL1, and JNK2." (PMID 32917965, 2020). "However, some actionable targets can be present in other genes (notably MET, RET, NTRK, and HER2), allowing inclusion into clinical trials of patients with EGFR, ALK, ROS1, and BRAF wild-type tumors with less than 50% PD-L1-positive tumor cells." (PMID 32294880, 2020). "Hsp70-mediated ubiquitination and degradation of oncoproteins, such as epidermal growth factor receptor, HER2, and hypoxia-inducible factor-1α, might provide Tid1 with tumor suppressor ability." (PMID 33233689, 2020). "Patients with EGFR alterations reported in tissue but not in plasma tended to have lower tumor burden as indicated by lower DNA yields from blood and a lower proportion of patients with evidence of disease in two or more organs." (PMID 32596507, 2020). "In the present study, we have analysed HIF1α, EGFR and pEGFR protein expression and EGFR gene copy number in HPV-negative LA-HNSCC patients to establish a correlation between these tumour biomarkers and treatment response to cisplatin radiation and nimotuzumab plus cisplatin radiation." (PMID 32939054, 2020). "EGFR and HER4 can activate PI3K after their binding to RTKs, especially by transphosphorylation of HER3, which can act as a critical partner for HER2 in the genesis and progression of the tumor." (PMID 33375317, 2020). "We hypothesize that in our in vivo T11 model, EGFR and HER2 signaling may modulate PD-L1 expression in tumor cells." (PMID 32923684, 2020). "Considering the production of circulating PD-L1 was reported to be correlated with stimulation with interferon-γ, it is understandable that EGFR-TKI treatment did not decrease sPD-L1 levels like membrane PD-L1 on tumor cells do." (PMID 32983977, 2020). "Since inhibiting EGFR activity promotes autophagic degradation of SOX2, we wondered whether the tumor inhibiting effect of gefitinib could be reversed by blocking autophagy." (PMID 31823521, 2020). "The authors demonstrated that the Enb-TRAIL bi-functional molecule simultaneously engages both EGFR and DR5 on the surface of tumor cells, leading to amplification of the apoptotic signal and proving to be more effective than a combination treatment with Enb and TRAIL." (PMID 33117154, 2020). "Alternately, as a substrate protein of EGFR, ANXA1 may contribute to neoplasm growth via autocrine and paracrine effects and sustain the preinvasive properties of malignant cancers through autocrine signaling induced by the N-terminal peptide." (PMID 32226026, 2020). "Clinicopathological characteristics, driven genes’ status (EGFR, ALK, and ROS1), adjuvant chemotherapy strategy for 94 surgical resected LCNECs were extracted from digital database, tumor relapse or progression, and survival were analyzed with clinical profiles." (PMID 33335851, 2020). "Moreover, we found that TMEM167A inhibition in this subgroup of GBMs reduced the EGFR–AKT signaling axis and impaired tumor growth." (PMID 31947645, 2020). "However, the influence of PGRMC1 on EGFR/HER2 signaling in lipid rafts and its impact on tumor progression requires further studies." (PMID 32660617, 2020).
tumor (continued). "The further intravasation of the tumor cells within the blood vessel is also mediated by macrophages; inhibition of the paracrine loop between CSF-1 and EGF through silencing of epidermal growth factor receptor (EGFR) signaling results in blocked intravasation." (PMID 32477352, 2020). "This prompted the FDA to approve pembrolizumab as a first-line treatment for PD-L1+ (≥50%) NSCLC with no EGFR or ALK genomic tumor aberrations in 2016." (PMID 33322522, 2020). "Although the EGFR and CCND1 (cyclin D1) loci were triploid, and the MET locus was triploid with LOH, the transcriptome analysis showed only MET RNA overexpression in this tumor, contrasting with the findings from F8." (PMID 31963394, 2020). "This suggests that the FGF2‐FGFR continuous activation of the downstream network signal pathway through bypass and the growth of the tumor cells is not restricted by the inhibitory effect of EGFR‐TKI." (PMID 32163227, 2020). "In contrast, some reports have shown that CEA levels do not respond to tumor progression during EGFR-TKI treatment." (PMID 32034239, 2020). "We found that radiotherapy alone can slightly increase the expression levels of EGFR and AKT in C33A cells, which may be due to accelerated tumor cell proliferation, anti-apoptosis, and radiation resistance caused by radiation." (PMID 32850421, 2020). "SIAHON expression indicates persistent EGFR/RAS/RAF/MEK/MAPK pathway activation and cancer cell proliferation and predicts for tumor progression, whereas SIAHOFF expression indicates EGFR/RAS/RAF/MEK/MARK pathway inactivation, diminished cell proliferation, and tumor regression." (PMID 32846967, 2020). "EGFR expression (regardless the activation status) was not modified by the antibody, either on the skin or tumor biopsies." (PMID 32537431, 2020). "By the standard clinical pipeline, no tumor-specific genetic alterations were identified except equivocal amplification of EGFR." (PMID 32490123, 2020). "Therefore, we now explore the effects of introducing the EGFR and PDGFRA amplified sub-populations away from the centre of the tumour where there is less competition for space." (PMID 33120534, 2020). "Anti-EGFR therapy has not resulted in any benefit in RAS-mutated tumors, irrespective of the primary tumor location." (PMID 32498251, 2020). "Therefore, EGFR/PI3K/AKT signalling enhances glucose entry and glycolysis to drive tumour metabolism." (PMID 32002123, 2020). "In addition to the EGFR, insulin-like growth factor 1 (IGF1-R) contributes to the malignancy and invasion of tumor cells by stimulation of EMT mechanism." (PMID 32503307, 2020). "Of note, EGFR expression and tumor perfusion were not added to these analyses, as these data were only available for a limited number of lesions." (PMID 31705176, 2020). "By this reasoning, MIA PaCa-2 tumours, having a lower abundance of EGFR, would not deplete the inward flux of CTX-MMAE to as great an extent as PANC-1; therefore, greater numbers of cells would be eradicated, resulting in greater overall efficacy." (PMID 32913288, 2020). "Also, clinicopathological characteristics of patients indicated that the EGFR expression was significantly correlated with the smoking status and WHO grades of the patients (P < 0.05), increased dramatically in tumor stages of III–IV." (PMID 32820249, 2020). "In the present study, EGFR‐specific CAR NK cells (EGFR‐CAR NK cells) were generated by fusing the scFv of an anti‐EGFR antibody to the artificially combined receptor molecules, in order to examine their anti‐tumor effects on TNBC cells." (PMID 32592435, 2020). "Interestingly, CTLA-4-positive SK-BR-3 and LNCaP cancer cells showed higher levels of EGFR than those detected on cells expressing low levels of CTLA-4, such as tumor MCF-7 cells or H9c2 cardiomyoblasts." (PMID 32024070, 2020).
tumor (continued). "Mechanistically, the phosphorylation of EGFR can stimulate several downstream signaling pathways, including MAPK/MEK/ERK and PI3K/AKT, that are involved in a variety of mitogenic, metastatic, and other tumor-promoting cellular activities." (PMID 32373608, 2020). "Unlike endorepellin, which has no direct effects on cancer cells, decorin also binds EGFR and Met receptors expressed on tumor parenchyma and inhibits tumor growth and development through stunting proliferation and angiogenesis while activating mitophagy." (PMID 33020183, 2020). "This cooperation appears to be specific to Yki-induced tumors as there was no cooperation with other oncogenic drivers such as EGFR or activated Notch in wing disc tumor models." (PMID 32737120, 2020). "Furthermore, preclinical studies reported an immune modulatory effect of EGFR signaling by regulating expression of MHC I/II and PD-L1 on tumor cells and the activity of T-cells." (PMID 32760402, 2020). "EGFR is another RTK that undergoes subcellular trafficking from the cell surface to the nucleus, Golgi, or endoplasmic reticulum and influences transcriptional regulation, tumor progression, and drug resistance." (PMID 33019722, 2020). "This conclusion was supported by that abrogating HER3 upregulation in response to EGFR antagonist could inhibit the proliferation of TNBC cells and attenuates tumor growth in a mouse xenograft model." (PMID 32917240, 2020). "Another study has been reported that there was a significant correlation between EGFR negative tumor and positive radio therapeutic response at 3-month check cystoscopy." (PMID 32795296, 2020). "Overexpression of EGFR activates downstream signaling pathways including PI3K/AKT and MEK/ERK signaling, resulting in aggressive growth and invasive related phenotypes in cells, such as tumor cell motility, adhesion, metastasis, as well as angiogenesis." (PMID 33292235, 2020). "These landscapes are considered “stable” because they have not generated an identified tumor with an EGFR exon 19 deletion in either of the two patients (four haploid genomes) used in this study." (PMID 31940362, 2020). "Many of them such as platelet-derived growth factor (PDGF), epidermal growth factor receptor (EGFR), vascular endothelial growth factor (VEGF) α, β, and fibroblast growth factor receptor (FGFR) are strongly involved in tumor stroma functions, vascular endothelial formation, and angiogenesis." (PMID 33293516, 2020). "Cetuximab-mediated ADCC highly correlates with EGFR surface expression in cell lines but clinical response in patients appear to be independent of tumor EGFR expression level." (PMID 32698317, 2020). "Erlotinib is a HER1/EGFR-specific reversible TKI that binds to the cytoplasmic ATP pocket domain of the receptor, blocking cell-cycle progression, inducing apoptosis and suppressing the growth of human tumor cell lines and xenografts models in mice." (PMID 32592373, 2020). "MDM2 amplification may activate the bypass signaling pathways, inhibit tumor cell apoptosis, promote the epithelial to mesenchymal transition (EMT) process and tumor angiogenesis and contribute to primary resistance to EGFR-TKIs." (PMID 32611363, 2020). "Given the close association of CD151 with oncogenic drivers including growth factors, such as EGFR, HER2, and HGFR (c-Met), CD151 was shown to impair growth factor receptor-dependent processes such as tumor onset, cell growth, spreading and motility." (PMID 32117989, 2020). "lnc-EGFR via regulating AP-1/NF-AT1/Foxp3 signaling pathway and lncRNA SNHG1 by regulating miR-448/IDO affect the differentiation and growth of immunosuppressive regulatory T cells (Tregs) and enable immune escape for tumor." (PMID 33281872, 2020).
tumor (continued). "We also note that in this work we have avoided modelling single cell events in a macroscopic setting, by assuming that each of the EGFR and PDGFRA amplified sub-populations only become established within a tumour at most once and introduce a small distribution of cells accordingly." (PMID 33120534, 2020). "The PPA below 80% supports reflex tumor tissue testing when a liquid test is negative, similar to the Cobas EGFR test." (PMID 32596507, 2020). "Among the clinical sub-groups, the concordance rate and the sensitivity of EGFR plasma test were higher in patients with Ecog PS ≥ 2, pleural effusion, and tumor size > 5 cm compared to others but not with statistical significance (P > 0.05)." (PMID 32746896, 2020). "EGFR amplification is one of the most common genetic aberrations in GBM, which has garnered this gene locus significant attention for both a possible molecular marker for tumor outcomes and a potential target for treatment." (PMID 33235995, 2020). "Additional genetic alterations can co-exist with a primary targetable oncogenic “driver” alteration (e.g., oncogenic EGFR, ALK, KRAS) and may help promote tumor progression and limit therapy response." (PMID 32822576, 2020). "Fusion of anti-EGFR nanobodies have increased therapeutic efficacy of platinum prodrugs and cucurmosin, and anti-MHC-II nanobodies fused to the drug DM1 have also exhibited significant targeting and tumor cytotoxicity." (PMID 32793488, 2020). "Since oncogenic driver alterations may modulate immune response in tumor microenvironment that may influence prognosis in LUAD, the effects of EGFR, ALK, ROS1, and BRAF alterations on tumor microenvironment remain unclear." (PMID 33585210, 2020). "An EGFR mutant tumor without pure EGFR dependency is a tumor with genomic instability, as a result of which the prognosis for this patient group is poor." (PMID 32277151, 2020). "Soon, a re-challenge strategy using anti-EGFR therapy may be active in patients with RAS and BRAF wild-type tumours, who have acquired resistance to first-line cetuximab-based therapies." (PMID 32605298, 2020). "In the case of left- or right-sided primary tumors, there was no statistical difference in OS between EGFR-low and EGFR-high tumor cases (respectively)." (PMID 32155907, 2020). "We found that foci cells 1- have a higher mitotic index (Ki67+ cells) and vascular density, 2- can show sign of hypoxia (HIFα staining), 3- can have frequent chromosome 7 polysomy as well as higher intensity for EGFR and AKT stainings compared to the rest of the tumour." (PMID 32218467, 2020). "Mechanistically, a lot of tumor- and TME-derived signals, such as hypoxia, EGFR-induced STAT3 and NF-κB activation, might be responsible for upregulated NEAT1 expression." (PMID 32843056, 2020). "As most marketed anti-EGFR mAbs are targeted on Domain I/III of EGFR ECD, this may explain why the epitope has anti-tumor activity in HCC, distinguishing it from anti-EGFR antibodies and TKIs." (PMID 32079107, 2020). "Recent studies suggested that EGFR was dysregulated in many different tumor types, including melanoma, breast cancer, non-small cell lung cancer and colorectal cancer." (PMID 32962742, 2020). "A previous study, using SPECT, demonstrated that tracer dose of anti-EGFR mAbs without pre-dose was almost entirely absorbed by the liver, hampering tumor visualization." (PMID 31705176, 2020). "In addition, HME primary tumor maintained the same pattern after TT, whereas 14 LME patients changed in high c-MYC expression after anti-EGFR therapy (decremental percentage of almost 60%)." (PMID 32164324, 2020). "A retrospective study has confirmed that there is a significant increase in epidermal growth factor (EGFR) detection rate for CB compared to FB, but CB and FB have not yet been compared in terms of molecular genetic tumor characterization." (PMID 32640669, 2020).
tumor (continued). "While this could be the case, a study reconstructing the phylogeny of GBMs identified EGFR and PDGFRA amplification as early and late events during tumour progression." (PMID 33120534, 2020). "Analysis of CTCs tumor gene expression also revealed over-expression of EGFR and/or VEGFR in 51% of patients, not previously submitted to target therapy, of which 30% (10 patients) were successively treated with third-line targeted therapy." (PMID 32088781, 2020). "EGCG downregulated molecular signaling factors such as epidermal growth factor receptor (EGFR), extracellular signal-regulated kinase 1/2 (ERK1/2), and mitogen-activated protein kinase (MAPK) and inhibited tumor microvessel density dose-dependently in xenografts of these cells." (PMID 33027981, 2020). "Recently, atezolizumab in combination with bevacizumab, paclitaxel, and carboplatin was approved for the first-line treatment of adult patients with metastatic non-squamous NSCLC with no EGFR or ALK genomic tumor aberrations." (PMID 32448366, 2020). "Reports from other authors have shown that lapatinib, a dual inhibitor of EGFR and HER2, combined with the mTOR inhibitor rapamycin induced significant in vitro growth inhibition of TNBC cell lines and synergistically reduced tumour growth in TNBC cell-derived xenograft models." (PMID 32286420, 2020). "Tumor growth assays were performed by inoculating the TNBC cell lines into the breast fat pad of the female nude mice that were injected with EGFR‐CAR NK cells or Con‐CAR NK cells on days 14, 21, 28, and 35 to assess the possible role of EGFR‐CAR NK cells in inhibition of CLDX TNBC tumor growth." (PMID 32592435, 2020). "In fact, EGFR activation contributes to the upregulation of PD‐1, PD‐L1, and CTLA‐4 expression levels as well as the decrease in T cell infiltration and reduces inflammation in the tumor microenvironment." (PMID 32997401, 2020). "Similarly, bispecific light T-cell engagers (LiTEs) targeting EGFR and CD3 have demonstrated T cell-mediated tumor lysis with minimal cytotoxicity." (PMID 32793488, 2020). "Interruption of EGFR signalling can prevent the growth of tumours expressing EGFR and improve patients’ condition, so not surprisingly, EGFR has emerged as a principal target for therapeutic intervention." (PMID 33113804, 2020). "Although the specificity of these PCR-based platforms allows for the initiation of EGFR-targeted therapy on the basis of positive plasma testing, negative results must be confirmed by tumor tissue genotyping." (PMID 32010431, 2020). "There was no statistical difference of OS between HAS and non-HAS by using multivariable Cox regression models given the following covariance: age, tumor location, surgery type, vascular invasion, T and N stage, the level of CEA and CA199, EGFR and neoadjuvant chemotherapy." (PMID 32680468, 2020). "The findings also indicate that miR-1224-5p inhibits cell proliferation, colony formation, migration and invasion in vitro and tumour growth in vivo by targeting TNS4, and subsequently promoting the autophagic degradation of EGFR, and suppressing downstream EFNA1/EPHA2 and VEGFA signalling pathways." (PMID 32732965, 2020). "KEYNOTE-042 included NSCLC with locally advanced or metastatic disease without previous treatment and without a driving mutation in EGFR or ALK translocation, and with PD-L1 tumor proportion score (TPS) of 1% or greater." (PMID 33171686, 2020). "In the EGFR(+) tumors, targeted agent tumor uptake showed no capacity to distinguish treated and untreated animals." (PMID 33042280, 2020). "HGK down-regulated EGFR and slowed down the growth of tumors, but not the total inhibition of tumor growth." (PMID 32093124, 2020). "In a GEPIA analysis, we additionally determined that there was a significant positive correlation between the expression of EGFR and lncZEB-AS1 in HCC patient tumor samples, suggesting that this lncRNA may promote HCC progression via an EGFR-PI3K-AKT axis." (PMID 32742459, 2020).